STAT3 (signal transducer and activator of transcription 3)
Diseases named in the same sentence as STAT3 in open-access papers (continued):
Sharing a sentence is not in itself a finding about the gene and the disease.
tumor (continued). "The inhibition of JAK2/STAT3 signaling pathway contributed to the anti-tumor effect produced by miR-218." (PMID 30314496, 2018). "NF-κB and STAT3 are activated in most cancers and are required for regulating genes involved in tumor proliferation, survival, angiogenesis, invasiveness, motility, and chemokine and cytokine production." (PMID 29636841, 2018). "Consistently, OP-D treatment significantly reduced NSCLC tumor growth in preclinical mouse model with via decreasing levels of p-STAT3." (PMID 30413072, 2018). "Such aberrant activation of STAT3 contributes to tumour initiation, progression, immune evasion and metastasis." (PMID 29630659, 2018). "RFP imaging indicated that the tumor volumes in xenotransplanted GBM-R2I2/sh-STAT3 mice were significantly shrunken compared with those of GBM-R2I2/sh-Scr-injected mice after 5 Gy RT." (PMID 30551687, 2018). "STAT3 is a major contributor for the formation of HCCs, since STAT3 has been shown to increase cell proliferation and tumor angiogenesis, while decreasing apoptosis and reducing activation of antitumor immunity." (PMID 30072615, 2018). "Altogether, such findings indicate oncogenic overexpression of FGFR as an additional signaling pathway to induce aberrant STAT3 activation in tumor cells and suggest therapeutic strategies to treat FGFR-overexpressing cancers." (PMID 29914167, 2018). "We demonstrated that the negative regulation of STAT3 activity by Hst correlates with increased recruiting of tumoricidal macrophages into the tumor microenvironment." (PMID 29963254, 2018). "Accordingly, RKIP expression has been found to be inversely correlated with phosphorylated STAT3 (pSTAT3) levels in different tumor types." (PMID 30149591, 2018). "Meanwhile further phosphorylation of Stat3 was observed in mouse tumor tissue and human lymph node metastases." (PMID 29970138, 2018). "In continuation with our efforts to characterize the novel and efficacious blockers of STAT3 activation, this study aimed to investigate the effects of OP-D on the tumor growth in a NSCLC mouse model." (PMID 30413072, 2018). "Another example of the role of STAT3 as an integrator can be seen in a phenomenon referred to as ′TGF-β switch′ in which TGF-β appears to have tumor suppressive effects in epithelial cells, whereas in tumor cells it is pro-tumorigenic." (PMID 30081609, 2018). "Based on the most recent literature, depending on the tumor cell type, the local microenvironment status, and the stage of the disease, either STAT3 activation or inactivation can support disease progression." (PMID 30231553, 2018). "Activation of STAT3 plays a crucial role in the progression of human epithelial ovarian cancer by regulating macrophage polarization in the tumor microenvironment." (PMID 29892301, 2018). "Although CES2 has been shown to express within tumor tissue, our data demonstrate that Hst can synergize the tumor inhibition of CPT-11 through negative regulation on tumor STAT3 activity." (PMID 29963254, 2018). "Expressions of Notch 1 and Jagged1 were positively correlated with p-STAT3 levels in primary tumor tissues." (PMID 29849934, 2018). "STAT3 signaling also plays an important role in the regulation of the cancer stromal and immune cells of the tumor microenvironment." (PMID 30446007, 2018). "Aberrant activity of STAT3 correlates with tumor growth, invasion and metastasis, which makes it a potential therapeutic target of cancer." (PMID 29636641, 2018). "The combination of RT and STAT3 knockdown had a synergistic effect, significantly reducing tumor volumes." (PMID 30551687, 2018). "Overall, these results suggest a critical role for estrogen signaling in maintaining an anti-tumor microenvironment, thereby decreasing K-ras lung tumor development following Stat3 deletion in female mice." (PMID 30389925, 2018). "More importantly, activation of the JAK/STAT3 pathway is a necessary condition for the recruitment of MDSCs to tumor cells and exertion of their immunesuppression." (PMID 30581487, 2018).
tumor (continued). "PTPRD has been characterized as a tumor suppressor gene in MM and a homozygous deletion in PTPRD encoding locus is known to modulate phosphorylation of STAT3 that promotes IL6 signaling." (PMID 30134812, 2018). "The results indicate that STAT3 siRNA can silence STAT3 gene of B16F10 cells, however, it must be first transferred into B16F10 cells via carrier, and PEI is an effective vehicle for transferring STAT3 siRNA into tumor cells." (PMID 29348670, 2018). "STAT3 activation requires phosphorylation of a tyrosine residue through JAKs and TYK2 kinases and constitutive STAT3 activation in tumor cells provides mitogenic and pro-survival signals." (PMID 30420593, 2018). "Our findings suggest that OP-D can induce apoptosis and exert anti-tumor effects by inhibition of STAT3 signaling pathways in NSCLC." (PMID 30413072, 2018). "Excessive JAK/STAT3 signaling promotes cancer cell proliferation, survival, angiogenesis, tumor metabolism, and antitumor immunity suppression." (PMID 30564118, 2018). "This important transcription factor (STAT-3) controls tumor cell proliferation, angiogenesis, and immune tolerance, thereby constituting a bridge between oncogenesis and immunosuppression." (PMID 30477198, 2018). "Although further studies are needed to understand the exact molecular pathways underlying the action of pterostilbene, our study provide novel potential applications for pterostilbene as a small molecule inhibitor of STAT3 with anti-tumor activity." (PMID 29986501, 2018). "In conclusion, our data suggest that cancer-derived exosomal gp130 plays a critical role in the tumor environment via activation of the IL-6/STAT3 pathway in macrophages." (PMID 29867925, 2018). "STAT3 signaling pathway plays an important role in tumor-related activities, such as cell proliferation, migration, invasion and metastasis." (PMID 30555277, 2018). "Overall, sustained abnormal activation of STAT3 can inhibit tumor cell apoptosis, promote tumor cell proliferation, and enhance angiogenesis." (PMID 29348670, 2018). "IL-17 induces IL-6 production by tumor-infiltrating immune cells and tumor cells and activates the signal transducer and activator of transcription 3 (Stat3)-dependent pathway that subsequently enhances tumor cell growth." (PMID 29515773, 2018). "Phosphorylated STAT3 then dimerizes and translocates into the nucleus to induce transcription of a set of downstream genes, which play crucial roles in promoting tumor cell proliferation and survival, tumor invasion, angiogenesis, and immunosuppression." (PMID 30143645, 2018). "Because of the particular abundance of macrophages at the tumor edge, we found that in the Hst-treated immunocompetent mice, suppressed expressions of p-STAT3 were correlated with a significant increase in macrophage infiltration at the tumor edge (R2=0.97)." (PMID 29963254, 2018). "Several results suggested that the role of SIRT2 in tumour angiogenesis is dependent on the STAT3/VEGFA signalling pathway." (PMID 30584257, 2018). "STAT3 is a transcription factor with important immune-regulatory activity in tumor and tumor microenvironment-immune cells facilitating angiogenesis, tumor cell proliferation, and survival." (PMID 30340426, 2018). "Transducers and activators of transcription 3 (STAT3) overexpression have been reported in many tumor types, suggesting that STAT3 inhibition can have an anticancer effect." (PMID 30104534, 2018). "Constitutively activated STAT3 has been observed in numerous primary tumor cells as well as in tumor-derived cell lines obtained from patients, including those with lymphoid malignancies." (PMID 30123428, 2018). "Like STAT3, the transcription factor NF-κB is aberrantly activated in many types of cancers, where it regulates, among others, genes involved in tumor cell proliferation, migration, and invasion." (PMID 29914167, 2018).
tumor (continued). "The signal transducer and activator of transcription 3 (STAT3) signaling pathway is widely known to be involved in inflammatory and anti-inflammatory responses, tumor progression and cell autophagy." (PMID 29497350, 2018). "A HDAC6-specific inhibitor called KA2507, inhibits tumor growth through regulation of aggresome formation, and inhibition of PD-L1 expression via decrease of STAT3 phosphorylation." (PMID 30096875, 2018). "Several lines of evidence indicate that the NF-κB and JAK/STAT3 pathways mediate the expression of inflammatory cytokines, such as IL-6, that flame the tumor microenvironment." (PMID 29707119, 2018). "Stimuli from proinflammatory cytokine IL-6 expressed by tumor cells, is sufficient to induce the expression of Twist1 in normal fibroblasts and transdifferentiate them into CAFs through the activation of STAT3 pathway." (PMID 30175384, 2018). "In conclusion, STAT3/Slug regulates radioresistance and induces tumorigenesis, tumor invasion, and CSC properties." (PMID 30551687, 2018). "By modulating the transcription of many genes that regulate a wide variety of biological processes, including cell proliferation, apoptosis, metastasis, and the immune response, the STAT3 oncoprotein drives tumor progression and chemoresistance in EOC." (PMID 28388577, 2017). "Th17-derived IL-17 can stimulate STAT3 signaling or promote myeloid-derived suppressor cell, both nurturing tumor microenvironments." (PMID 27935860, 2017). "This continuously activated state of STAT3 pathway promotes tumor cell growth, migration, invasion, angiogenesis, metastasis, and drug resistance, but inhibits apoptosis." (PMID 27861147, 2017). "Long-palate, lung and nasal epithelium clone 1 (LPLUNC1), a promising candidate tumor suppressor gene was associated with tumorigenesis of NPC; LPLUNC1 inhibited proliferation and promoted apoptosis by suppressing the Stat3 pathway in NPC cells." (PMID 28360411, 2017). "Signal transducer and activator of transcription 3 (STAT3) promotes tumor progression in many types of cancer." (PMID 28032598, 2017). "Since, activated STAT3 protects tumor cells from apoptosis and promote cell growth by regulating multiple genes associated with cell proliferation and anti-apoptotic proteins such as surviving cyclin D1,c-Myc, Fas, Mcl-1, Bcl-xL, and Bcl-2." (PMID 29254150, 2017). "An aberrant IL-6/STAT3/lncTCF7 signaling axis, in which IL-6 in tumor microenvironment induces lncTCF7 via activating STAT3, contributes to hapatocellular carcinoma cells aggressiveness through EMT induction." (PMID 27992370, 2017). "This was in paralleled with the result that maturation of DCs with LPS in the presence of CTLA-4-Fc resulted in robust phosphorylation of STAT3 and incubation of DCs with tumor lysates increased ERK phosphorylation." (PMID 28099147, 2017). "The expression of STAT3 was significantly correlated with the tumor size, pathological satellite, vascular invasion, undifferentiated-type histology, lymph node metastasis and TNM stage." (PMID 28032598, 2017). "In 3 studies documented in Oncomine data base, the expression of STAT3 at mRNA level (detected by microarray) in tumor samples was significantly higher than in counterpart normal lung tissues." (PMID 27835873, 2017). "Independent studies showed that tumor cells acquire metastatic potential through IL-6/STAT3 pathway." (PMID 29245982, 2017). "It has more recently been demonstrated that LIF induces the expression of miRNA-21, a miRNA that promotes EMT through STAT3 signalling in human tumor cells and was shown in our ISH experiments to be expressed at similar levels in all three classes." (PMID 28415643, 2017).
tumor (continued). "Our results suggested that the tumor suppressive effect of GMI was mediated through inhibition of IL-6/Stat3 signaling pathway." (PMID 29050290, 2017). "In fact, tumor‐infiltrating lymphocytes, including NK cells, display constitutive STAT3 phosphorylation, which is often driven by the production of cytokines, and growth factors by malignant cells." (PMID 28695716, 2017). "IL-6, one of SASP factors, is a pro-inflammatory signaling protein that encourages tumor growth, and exerts its oncogenic activity by triggering downstream STAT-3 and ERK pathways." (PMID 28273155, 2017). "JAK1-dependent STAT3 activation has been reported to promote tumor cell cycling, survival, and invasiveness, enhance telomerase activity and modulate angiogenesis." (PMID 28720093, 2017). "Two targets, IL-4Rα and cannabinoid receptor 2 (CB2), were validated and confirmed to regulate both IL-6 and IL-10 production in TAMs, contributing to autocrine/paracrine activation of STAT-3 in macrophages and tumour cells." (PMID 28381274, 2017). "The oncogenic EGFR signaling in NSCLC engages the activation of downstream effectors such as AKT-mTOR, ERK and STAT3 to promote cell proliferation, cell survival, and tumor growth." (PMID 29177004, 2017). "It is a negative regulator of nuclear factor-kappa B (NF-kB) and MAPK signaling pathways in CD44-positive tumor cells, and a positive regulator of Sarcoma (Src) and STAT3." (PMID 28445439, 2017). "Here, we show that in vivo inhibition of STAT3 by S3I-201 effectively delays tumor growth in ASCC mouse model indicated by significantly smaller tumor size and burden in the treatment group compared with control group at the same point." (PMID 28747781, 2017). "STAT3 is one of the best studied oncogenic signaling nodes, and it exerts enormous influence on tumor growth properties, including the support of stemness in diverse cancer types including those of breast, prostate, and brain." (PMID 28100038, 2017). "It has demonstrated that TAMs activate the STAT3 signaling in hepatocellular carcinoma cell lines results in larger tumor size, intrahepatic metastasis and high recurrence rate of the tumor." (PMID 28216578, 2017). "We found constituitve STAT3 activation, indicated by nuclear pSTAT3 immunostaining in control tumours, but increased pSTAT3 positive tumour epithelial cells in tissues from mice treated with IL11." (PMID 28186993, 2017). "STAT3 plays a major role in promoting tumor immune evasion since it not only has opposite effects to immunostimulatory STAT1 but also induces the secretion of immunosuppressive soluble cytokines that induce a tolerant TME." (PMID 28611673, 2017). "In TAs of (+)-JQ1-treated tumor-bearing mice, STAT3 activatory phosphorylation (p < 0.0001, one-way ANOVA) and expression of the STAT3 target suppressor of cytokine signaling 3 (SOCS3) (p < 0.0001, one-way ANOVA) were significantly reduced." (PMID 29167426, 2017). "Recently, a group of selective small molecule inhibitors targeting the DNA-binding domain of STAT3 has been identified and shown to inhibit cell proliferation and migration in vitro and tumor development in vivo." (PMID 29262529, 2017). "Reducing p-STAT3 expression can not only significantly inhibit tumor cells proliferation, but also migration and invasion in RCC." (PMID 29312589, 2017). "Stat3 displayed a higher expression compared to pStat3, which strongly labeled the nuclei of the endothelial cells and clusters of tumor perivascular cells in the same area." (PMID 28415725, 2017). "For example, STAT3, which is hyper-activated in a number of human malignancies, regulates the expression of numerous oncogenic genes that promote tumor progression." (PMID 27458171, 2017). "In vitro and in mouse tumor models STAT3 is integrally involved in tumorigenesis, including apoptosis, cell cycle progression, tumor angiogenesis, invasion and metastasis." (PMID 28709401, 2017).
tumor (continued). "Constitutively activated STAT3 promotes carcinogenesis and STAT3 overexpression has been reported in many tumor types." (PMID 28514737, 2017). "The IL-6/IL-6R/STAT3 pathway mediates interactions between tumor cells and the TME and contributes to the development of drug resistance." (PMID 28928376, 2017). "IL-6 contributes to tumor metastasis via the JAK/Stat3 signaling pathway, and IL-10 phosphorylates of Stat3 in PCNSL cells, while the role of IL-6 in PCNSL remains poorly defined." (PMID 28415725, 2017). "We demonstrate that genetic silencing of STAT3 in the human tumor compartment can mediate enhanced infiltration of human T cells into the developing human tumor in vivo." (PMID 28008146, 2017). "On the other hand, STAT3 inhibition with galiellalactone significantly reduced tumor growth and early metastatic dissemination of PCa." (PMID 29152153, 2017). "Many target genes of STAT3 are relevant to various human cancers where they play pivotal roles in many cellular processes including tumor growth and progression." (PMID 29348886, 2017). "Numerous studies showed the activation of STAT3 in a wide variety of tumors and the proposed role for STAT3 in tumor formation or progression is based on the link between its activation and transformation." (PMID 28709401, 2017). "CXCL12, CXCR4, JAK2, and STAT3 can not only play significant role in tumor cell or macrophage, but also other cells, such as T lymphocyte, neutrophils, tumor-associated fibroblast, and endothelial cells." (PMID 28630636, 2017). "The aim of this work was to analyze STAT3 PTMs at different tumor stages and their relationship with STAT3 cellular functions." (PMID 28489571, 2017). "Additional reported data suggested that CCL2 induced EMT through the activation of STAT3 signals and inhibited STAT3 signaling to reduce the invasiveness of tumor cells." (PMID 28757590, 2017). "Consistent with this, β-elemene inhibited tumor growth, phosphorylation of Stat3, expressions of DNMT1 and EZH2 in a mouse xenograft model." (PMID 28360411, 2017). "Since allo-antigen immune responses in the TME can confound the tumor growth rate in this allogeneic system, we tested the STAT3 signaling in primary HNSCC tumors using our autologous HNSCC tumor engraftment system." (PMID 28008146, 2017). "In the current study, in order to further confirm the relationship between the expression of STAT3 and lymph node metastasis, we examined STAT3 expression in 15 ICC primary tumor and lymph node metastasis tissues." (PMID 28032598, 2017). "Tumor-induced or IL-10-induced inhibition of DC functional maturation can be abrogated by blocking of STAT3 signaling." (PMID 28346397, 2017). "IL-22 promotes tumorigenic functions, by activating STAT3 phosphorylation and inducing mitogenic and other pro-tumor genes in several tumor lines, including BCC and SCC lines." (PMID 28445952, 2017). "Overall, this review provides mechanistic insights for the roles of STAT3 signaling in tumor angiogenesis." (PMID 28978186, 2017). "Previous studies have shown Stat3 as an important molecule in MDSC accumulation in tumor-bearing mice." (PMID 28055016, 2017). "The dysregulation of these genes because of the constant activation of both STAT3 and NF-κB in tumors and the tumor microenvironment is critical to tumor progression." (PMID 29194365, 2017). "STAT3 acts as an oncogene and promotes proliferation, survival, angiogenesis, and metastasis, and interferes with apoptosis and anti-tumor immune responses." (PMID 27835873, 2017). "A lot of novel small molecular inhibitors of STAT3 have been reported to suppress cancer cells and tumor growth, such as LLL12, LY5, XZH-5 and so on." (PMID 28430601, 2017).